TNF (tumor necrosis factor)
Diseases named in the same sentence as TNF in open-access papers (continued):
Sharing a sentence is not in itself a finding about the gene and the disease.
Sepsis (continued). "In sepsis, inflammatory mediators such as TNF-α and nitric oxide disrupt lymphatic pumping and reduce interstitial hydrostatic pressure, effectively halting washdown." (PMID 40806877, 2025). "TNF-α is one of the earliest cytokines to rise, generally peaking within 1 to 2 h after the onset of sepsis and returning to baseline levels within 4 to 6 h." (PMID 40566580, 2025). "Using the “irGSEA” package, we scored hallmark pathways: Macro_1_FCGR3A showed downregulation of IL6-JAK-STAT3 but upregulation of PI3K-AKT-mTOR and TNF-NFκB signaling, suggesting an anti‐sepsis role." (PMID 41332909, 2025). "TNF-α released during sepsis enhances methylation of the SERCA2 promoter region, leading to down-regulation of SERCA2 expression." (PMID 40356926, 2025). "For instance, in a mouse model of cardiac dysfunction induced by sepsis, pre-treatment with losartan reversed the increase in IL-1β, IL-6, TNF-α, and MCP-1." (PMID 40647187, 2025). "In humans, IL-4 and IL-10 levels rise during the recovery phase of SIRS and sepsis, although they typically remain lower than pro-inflammatory cytokines such as IL-6 and TNF-α." (PMID 40584120, 2025). "lncRNA H19 alleviates sepsis-induced acute lung injury by downregulating the expression of TNF-α, IL-6, IL-17, caspase-3, caspase-9, and Bax while upregulating Bcl-2 levels, thereby suppressing lung cell apoptosis and inflammation." (PMID 39940682, 2025). "Systemic inflammatory response syndrome triggered by sepsis ramps up the production of inflammatory signaling molecules like IL-6 and TNF-α, while simultaneously kicking the coagulation system into overdrive." (PMID 40959822, 2025). "It was reported that NF-κB is activated with TLR-4 and promotes the level of TNF-α, IL-16, and IL-6 in the tissue of sepsis rats." (PMID 41221897, 2025). "Serum and tissue levels of TNFα and TNFR1 are known to be markedly increased during sepsis in humans, rats, and mice, while it has been shown that Clock deletion reduces macrophage-derived TNFα." (PMID 39968295, 2025). "During the early phases of sepsis, pro-inflammatory cytokines such as tumor necrosis factor-alpha (TNF-α), interleukin-1β (IL-1β), and interleukin-6 (IL-6) are released, initiating the inflammatory cascade." (PMID 40566580, 2025). "TNF-α can reproduce all clinical signs of sepsis when administered systemically, underscoring its pivotal role in sepsis pathogenesis." (PMID 41196905, 2025). "The unexpected success of anti-TNF therapies in RA, born from sepsis research, serves as a powerful testament to the value of animal research." (PMID 40303397, 2025). "Recently, different types of biomarkers, such as tumor necrosis factor-α, IL-6, cluster of differentiation 64, and miRNAs, have shown clinical application in patients with sepsis." (PMID 40478618, 2025). "When sepsis occurs, NF-κB activation and the release of acute inflammatory cytokines including TNF-α and IL-1β inhibit FXR activity, leading to bile acid metabolism imbalance." (PMID 40430579, 2025). "The pathological expansion of MDSCs in sepsis is driven by sustained production of inflammatory factors like IL-6 and TNF-α, and the activation of signaling pathways such as STAT3 and NF-κB." (PMID 40364841, 2025). "Serum levels of IL-40, a newly identified biomarker, and TNF-α, a classical proinflammatory cytokine, were highest in the LPS group, corroborating the successful establishment of the sepsis model and paralleling CRP elevation (p < 0.001)." (PMID 41196905, 2025). "Circulating EVs notably exacerbate the inflammatory response to sepsis in both serum and lung tissue by enhancing the production of proinflammatory factors such as tumor necrosis factor-α (TNF-α), interleukin-6 (IL-6), and interleukin-1β (IL-1β)." (PMID 39967672, 2025). "ELISA was used to measure systemic inflammatory responses in sepsis model rats by determining concentrations of serum IL-6, IL-1β and TNF-α." (PMID 40582762, 2025).
Sepsis (continued). "In sepsis, inflammatory mediators such as TNF-α and IL-6 enhance TF expression on endothelial cells, promoting thrombosis." (PMID 40226813, 2025). "The sepsis-induced immune response produces an abundance of pro-inflammatory factors (TNF-α, IL-1β), which bind to specific receptors and activate apoptotic signaling pathways such as Fas and Caspase." (PMID 40823184, 2025). "A recent study indicates that during sepsis, the cytokine tumor necrosis factor (TNF) disrupts the homeostatic unfolded protein response (UPR) by activating the interferon (IFN) pathway, which diminishes the production of antimicrobial peptides." (PMID 40061452, 2025). "Severe leptospirosis develops a cytokine storm characterized by high levels of IL-6, TNF-α, and IL-10, resembling sepsis-like phenotypes." (PMID 41445751, 2025). "Examination of TNF-α levels revealed a substantial increase in the sepsis group compared to the healthy group." (PMID 39955435, 2025). "The hyperactivation of the immune system during sepsis leads to a cytokine storm, characterized by the excessive release of pro-inflammatory cytokines, including tumor necrosis factor-alpha (TNF-α), interleukin-1 beta (IL-1β), and interleukin-6 (IL-6)." (PMID 39803908, 2025). "In bacterial infections, particularly sepsis, IL-38 reduces the release of pro-inflammatory cytokines (IL-6, TNF-α, IL-17) and promotes regulatory T cell responses, thereby mitigating tissue injury and improving survival in experimental models." (PMID 41300951, 2025). "The CLP-induced sepsis model was examined in this study by assessing the pro-inflammatory cytokine TNF-α, antioxidant levels, lipid peroxidation rate, and MMPs." (PMID 39860018, 2025). "The experimental results showed that compared with healthy individuals, the levels of TNF‐α and NETs in the peripheral blood of sepsis patients were significantly increased." (PMID 40586264, 2025). "When sepsis occurs, the immune system activates and releases inflammatory factors such as tumor necrosis factor alpha, which activate transcription factor NF-κB in endothelial cells through signaling pathways." (PMID 40661134, 2025). "Our results showed that administering a single dose of amifostine as a pretreatment decreased TNF-α and TBARS levels and increased total thiol levels in sepsis associated with ALI." (PMID 39860018, 2025). "THCQ reduces key inflammatory factors in sepsis, such as TNF-α, IL-1β, and IL-6, inhibits oxidative stress, and alleviates iron overload, indicating its multiple protective mechanisms in mitigating the inflammatory cascade of sepsis." (PMID 40963685, 2025). "IL-17 (also known as IL-17A) is produced by IL-23-stimulated Th17 T cells after sepsis and induces the synthesis of various cytokines such as IL-1β, IL-6, and TNF-α." (PMID 40520010, 2025). "Regarding the prediction of mortality in patients with sepsis, the levels of corresponding proteins to the three upregulated necroptosis‐related genes showed excellent or considerable accuracy (AUC; TNF‐α = 0.904, PYGL = 0.851 and CYLD = 0.846)." (PMID 40318009, 2025). "Clavanin A and Clavanin-MO attenuate systemic inflammation and sepsis in murine models by downregulating pro-inflammatory cytokines such as IL-12 and TNF-α while upregulating the anti-inflammatory cytokine IL-10." (PMID 41440897, 2025). "In sepsis, the TNF-α/NF-κB pathway—an essential signaling axis that drives endothelial inflammation—is activated by ADAM17, thereby inducing endothelial inflammation, apoptosis, and barrier dysfunction." (PMID 41280722, 2025). "This meta-analysis demonstrated that dexmedetomidine exerts a positive effect on reducing interleukin-6 (IL-6) and tumor necrosis factor-α (TNF-α) levels in patients with sepsis, as well as lowering in-hospital mortality and 28-day mortality." (PMID 41195185, 2025).
Sepsis (continued). "TNF-α levels were 20.52 pg/mL in the sham group, 20.54 pg/mL in the sepsis group, 21.13 pg/mL in the pre-sepsis pomegranate group, and 23.02 pg/mL in the post-sepsis pomegranate group (p = 0.1)." (PMID 40896042, 2025). "When sepsis occurs, the inflammatory factors IL-6 and TNF-α released at the early stage in the body can bind with STAT3, activate it, and enhance IL-6 and TNF-α transcription in the nucleus." (PMID 40338919, 2025). "To confirm the anti-inflammatory activity of CBD in LPS-induced sepsis mouse model, we investigated the protein expression levels of inflammatory cytokines, such as TNF-α, IL-6, and IL-1β from the sepsis mouse serum samples." (PMID 41465451, 2025). "CSN6 upregulation increased IL-1β, IL-6, and TNF-α levels in an in vitro sepsis model (n = n = 6 per group)." (PMID 40595050, 2025). "These cytokines play a crucial role in sepsis, with IL-1β and TNF-α being pro-inflammatory factors that exacerbate systemic inflammation, while IL-6 is closely involved in the acute-phase response and immune modulation." (PMID 40422869, 2025). "The pathogenesis of sepsis and cytokine storm involves the excessive release of cytokines, including tumor necrosis factor-α (TNF-α), interleukin-1 (IL-1), interleukin-6 (IL-6), and interferon-γ." (PMID 41010563, 2025). "This meta-analysis demonstrated that ulinastatin significantly reduces mortality and inflammatory markers such as CRP, IL-1β, IL-6, IL-8, IL-10, PCT, and TNF-α in patients with sepsis compared to control group." (PMID 40667510, 2025). "Patho-physiologically, sepsis initiates an immune response and release of proinflammatory cytokines, such as tumor necrosis factor-alpha (TNF-α) and interleukins." (PMID 40573276, 2025). "IL-1β and TNF-α have been investigated for sepsis detection in febrile neutropenia, but consistent evidence from prospective and longitudinal studies has shown their limited diagnostic and prognostic utility." (PMID 40647525, 2025). "Nicotine suppresses the innate and adaptive immune response by reducing the secretion of pro-inflammatory cytokines (IL-1, IL-6, TNF-α), which reduces the activity of lymphocytes and decreases the possibility of cytokine storm and sepsis." (PMID 40650213, 2025). "Another study in septic calves also showed elevated TNF-α levels, and an increase in neutrophil counts has been associated with elevated TNF-α in sepsis." (PMID 41517447, 2025). "The values are presented as mean ± standard deviation for n = 9 animals in each group, at baseline (BL) and 8 h (*10 h for IL-6 and TNF) post-sepsis induction." (PMID 40993326, 2025). "Macrophages are recruited during sepsis, and release various inflammatory factors such as TNF, IL-1β and IL-6, along with chemokines like CCL6 and CD14, and the transcription factor NF-κB1." (PMID 40775729, 2025). "In sepsis patients, inflammatory factors like TNF-α and IL-6 are often significantly elevated, participating in inflammatory responses and potentially affecting immune cell functions." (PMID 41300910, 2025). "Our results showed that the expression of IL-10 on day +7 (P = 0.005), TNF-α and IL-6 on day +14 (P = 0.041 and P =0.010), and IL-6 on day +28 (P = 0.010) were higher in patients with sepsis than the control group." (PMID 40718494, 2025). "The combination of these tests increased the diagnostic accuracy of the combination of the WBC count and CRP level, proving useful in the diagnosis of sepsis and comparable to the use of IL-6 and TNF-α." (PMID 40806505, 2025). "Renal concentrations of TNF‐α, IL‐6, and IL‐1β were assessed in the Sham, sepsis and Cur + Sep groups." (PMID 41140036, 2025). "During sepsis, massive pro-inflammatory mediators (IL-6, TNF-α, etc.)drive hepatic acute phase response, leading to dramatic elevation of SF." (PMID 41323136, 2025). "Elevated levels of potent cytokines, including IL-6, IL-1β, and TNF-α, are detectable in patients diagnosed with early-stage sepsis." (PMID 41256846, 2025).
Sepsis (continued). "Previous sepsis research has largely focused on traditional biomarkers such as procalcitonin, C-reactive protein, IL-6, and TNF-α, which are critical mediators of the early inflammatory response." (PMID 40230692, 2025). "The possibility that central PI3K/MAPKs/TNFα signaling mediates the A3AR-nicotinic baroreflex interaction in sepsis was investigated." (PMID 40143165, 2025). "We investigated the role of several molecules involved in the ET stage after LPS challenge of whole blood and identified TNFα as a promising biomarker and a new variable to be included in modern algorithms for sepsis classification." (PMID 39559359, 2024). "In the initial stage of sepsis, an intense inflammatory response is ignited, leading to a surge of large amounts of inflammatory factors (e.g., IL-1β, TNF-α), which in turn creates a cytokine storm." (PMID 39720715, 2024). "In our study, it was observed that HCQ treatment drastically decreased the levels of IL-6 and TNF-α in sepsis-induced rats." (PMID 39596976, 2024). "Currently, TNF-α is the most studied and deeply understood cytokine in the research related to sepsis." (PMID 38848433, 2024). "The α7 controls systemic inflammation in sepsis by inhibiting TNF production and the NF-kB immunomodulatory response." (PMID 39636799, 2024). "B1a cells are able to secrete IgM as well as immunomodulatory cytokines like IL-10, spontaneously or after infection, and GM-CSF, IL-6, IL-3, TNF; therefore, there is evidence that B1a cells play a protective role in sepsis and survival benefits." (PMID 38474403, 2024). "Minocycline at 50 mg/kg significantly reduced TNF‐α expression compared to the Sepsis group (p = 0.016)." (PMID 39370294, 2024). "In a recent study, increased cytokine levels including TNF-α was identified as an indicator of poor prognosis and adverse outcomes in sepsis-induced brain dysfunction." (PMID 39549093, 2024). "During sepsis, dysregulated release of inflammatory cytokines such as tumor necrosis factor-alpha (TNF-α), interleukin-1 beta (IL-1β), interleukin-6 (IL-6), and interleukin-10 (IL-10) can contribute to harmful effects." (PMID 39597952, 2024). "Overall, sepsis strongly enhanced the IL-6 (> eightfold), TNFα (> 32-fold) and IL-1β (25-fold) gene expression." (PMID 39497013, 2024). "Strikingly, we find that the pairwise effects of tumor necrosis factor plus interleukin (IL)-18, interferon-gamma or IL-1β suffice to mirror the impact of sepsis across tissues." (PMID 38191855, 2024). "TNF‐α modulates cellular functions such as cell proliferation, survival, differentiation, and apoptosis, which has been well known to initiate sepsis." (PMID 39134731, 2024). "IL-1β, IL-6, and TNF-α are all potent proinflammatory cytokines that contribute heavily to organ dysfunction from sepsis." (PMID 38646937, 2024). "TNF-α and IL-1β serve as prominent inflammatory mediators initiating the immunopathological features of sepsis-induced shock." (PMID 39200042, 2024). "Other articles showed that the miR-31-5p/GSDMD Axis can regulate pyroptosis and miR-31-5p overexpressing can alleviate the level of TNF‐α, IL‐6 and IL‐1β in sepsis-induced pyroptosis." (PMID 38267979, 2024). "Systemic inflammation with an increase of the pro-inflammatory protein TNF was also observed, but the observed level was low compared to e.g., systemic infection as observed in sepsis." (PMID 39544322, 2024). "Taken together, these observations in sepsis and beyond help to contextualize the organism-wide effects of the three TNF-centered cytokine pairs identified by our data as critical to explain sepsis." (PMID 38191855, 2024). "In another experiment, nicotine inhibited the release of HMGB1 from macrophages induced by endotoxin or TNF-α by activating cholinergic signaling pathways, prevented NF-κB pathway activation, and improved the survival rate in experimental models of sepsis." (PMID 39206262, 2024).
Sepsis (continued). "In sepsis, B cells can produce a variety of pro-inflammatory cytokines like IL-6, TNF, IL-3, and GM-CSF, which amplify the systemic inflammatory response." (PMID 39664383, 2024). "The markers of M1 macrophage activation, TNF-α and IL-6, are significantly elevated in sepsis (Fig. EV4G)." (PMID 39294473, 2024). "The most commonly reported side effects of adalimumab, as well as other TNF-α inhibitors, include sepsis due to bacterial, fungal, and viral infections, opportunistic infections, pneumonias, pyelonephritis, septic arthritis, and tuberculosis." (PMID 39062219, 2024). "It has also been shown that ascorbic acid treatment suppresses the expression of inflammatory markers (sepsis and TNF-α) and markers of cellular damage, which is in accordance with the decreased levels of TNF-α in the CK group." (PMID 38732540, 2024). "The pathophysiology of sepsis is multifaceted, involving pro-inflammatory mediators such as tumor necrosis factor (TNF), interleukin-1 (IL-1), and interleukin-6 (IL-6), which are produced by the body in response to infection." (PMID 39205773, 2024). "Clinical studies have shown that intravenous Dex infusion reduces serum cytokine levels, including IL-1, IL-6, and TNF-α, as well as intra-abdominal pressure, to a greater extent than propofol infusion in patients with severe sepsis after abdominal surgery." (PMID 38419889, 2024). "Upon the onset of sepsis, AMs are activated and secrete a large number of inflammatory factors, such as tumor necrosis factor α (TNFα), interleukin-1β (IL-1β), and interleukin-6 (IL-6), triggering the inflammatory cytokine storm and tissue damage." (PMID 38725041, 2024). "TNF antibodies protect against lethal sepsis when present before or early on upon the start of the disease, but not later in the disease, which helps to explain the failure of anti-TNF therapy in humans with sepsis." (PMID 38191855, 2024). "The pathophysiology of sepsis is characterized by hyperactive and dysregulated endogenous inflammatory mediators, including IL-1β, IL-18, and TNF-α." (PMID 38584827, 2024). "Sepsis is a severe clinical syndrome due to the host response to infection, exacerbated by the production of both pro-inflammatory cytokines (TNF-alpha, IL-1-beta>alpha, IL-6, il-8, IL-12, IL-17, COX-2, IRF3) and anti-inflammatory (IL-10) cytokines." (PMID 39768405, 2024). "In murine models of sepsis, TNF-α levels sharply rise and peak remarkably early, within just 1–3 h, after LPS injection." (PMID 39056754, 2024). "While the first one is the least present in the population, with only 22% of patients with AKI-induced sepsis, the second one is the most frequent, with apoptosis as the main pathogenesis due to pro-inflammatory cytokines such as TNF-α and endotoxins." (PMID 38254870, 2024). "Specifically, our findings demonstrate that LBT exerts a significant inhibitory effect on lipopolysaccharide (LPS)-induced sepsis by suppressing the expression of key pro-inflammatory cytokines such as IL-6, TNF-α, and IL-1β." (PMID 38799158, 2024). "Throughout all explored tissues, sepsis increased pro-inflammatory cytokines like TNFα, MCP-1, IL-10 and IL-6 compared to sham animals, regardless of HVEM:LIGHT blockade." (PMID 38774873, 2024). "Another study showed that a murine sepsis model induced by cecal ligation and puncture stimulated NF-κB1, TNFα, and IL-6 activation in the livers." (PMID 38603936, 2024). "Some clinical trials have sought to treat sepsis by obstructing certain facets of the inflammatory response, such as tumor necrosis factor and interleukin-1, which are specific inhibitory targets, but the results have often been unsatisfactory." (PMID 39252831, 2024). "In this study, our findings demonstrated that LBT Lobetyolin effectively protects mice from sepsis induced by LPS by downregulating the production of pro-inflammatory cytokines such as TNF-α, IL-6, and IL-1β in macrophages." (PMID 38799158, 2024).